SPHK1 (sphingosine kinase 1)
Diseases named in the same sentence as SPHK1 in open-access papers (continued):
Sharing a sentence is not in itself a finding about the gene and the disease.
inflammation (8 papers, 2012 to 2022). Aberrant reaction of the microcirculation characterized by movement of fluid and leukocytes from the blood into extravascular tissues. "Altogether, these data suggest that the effect of SphK1 on the outcome of renal inflammation is still controversial and appears to be disease- and duration-dependent." (PMID 28282921, 2017). "In lung tissue lysate, we found that KC and IL-6 concentrations were basally elevated consistent with the constitutive neutrophilic lung inflammation seen in Sphk1−/− mice." (PMID 22355325, 2012). "The constitutive low plasma S1P concentration, and the significantly lower S1P concentration in experimental endotoxemia, might explain the PMN lung inflammation and the exacerbated lung inflammatory response to LPS seen in Sphk1−/− mice." (PMID 22355325, 2012). "Further, administration of SPHK1 inhibitor, SKI-II to mice attenuated bleomycin-induced lung inflammation and collagen deposition in lungs confirming a role for SPHK1-mediated S1P in the development of PF." (PMID 32549377, 2020). "In support of this, expression of proinflammatory markers (Cxcl2, Tlr4, MCP-1, Pcna, and Col3a1) was increased in the kidneys of wild type and Sphk1−/− mice but not in Sphk2−/− mice, suggesting a protective effect of SphK1 on renal inflammation." (PMID 35409370, 2022).
neurodegenerative disease (6 papers, 2014 to 2026). A disorder of the central nervous system characterized by gradual and progressive loss of neural tissue and neurologic function. "In previous studies, the role of SPHK1 has been extensively studied, particularly in relation to neuroprotection and neurodegenerative diseases SPHK1 is predominantly expressed in most tissues, where it regulates cell growth and survival." (PMID 41495814, 2026). "Taken together, these original data reveal an imbalance in SphK1/SPL system which might play a crucial role in neurodegenerative disease." (PMID 24468113, 2014). "The reported literature has highlighted an interesting point of similar changes in sphingolipids observed among AD, PD, HD, and ALS, and this opens new avenues to explore the Sphk1, COX2, and SPM trilogy, and N-AS signaling in other neurodegenerative disease as well." (PMID 34298977, 2021).
adenocarcinoma (5 papers, 2015 to 2024). A common cancer characterized by the presence of malignant glandular cells. "Unchangeable, negative relations of the HRH4 with SPHK1 were observed in both the control and adenocarcinoma colon." (PMID 36902343, 2023). "There was no observed association between SPHK1 IHC and histology and multivariate analysis did not suggest and differential effect of SPHK1 in squamous versus adenocarcinoma (although numbers were small in this analysis)." (PMID 26493335, 2015).
metabolic disorders (5 papers, 2020 to 2024). "Therefore, the role of Sphk1 in these metabolic diseases has not been fully elucidated, and more research is needed for further understanding." (PMID 33208918, 2020).
colorectal (4 papers, 2016 to 2022). "Sphk1 is responsible for phosphorylation of sphingosine and production of S1P, and it was shown that Sphk1/S1P signaling can induce colorectal carcinogenesis through activation of the interleukin-6/signal transducer and activator of transcription (STAT)-3/protein kinase B pathway." (PMID 33805921, 2021).
colon (3 papers, 2011 to 2019). "In this study, we investigated effects of SphK1 expression in intestinal epithelial cells on colon carcinogenesis." (PMID 28583134, 2017). "The result suggests that SphK1 plays an important role in tumorigenicity and that it may be necessary in the early stage of colon carcinogenesis." (PMID 28583134, 2017).
bacterial infection (2 papers, 2010 to 2021). "Based on the results obtained from RAW macrophages, we predicted a possible connection of SphK-1 with p38 for regulating bacterial infection." (PMID 20498849, 2010). "The SphK1 (but not SphK2) mRNA level significantly increased at 2, 4, or 8 h after bacterial infection." (PMID 33922596, 2021).
kidney disease (2 papers, 2024 to 2026). "SphK1, which is widely distributed in renal tissues and pivotal for downstream regulation, is a potential target for renal disease treatment." (PMID 39487526, 2024).
infectious disease (1 paper, 2021). A disorder directly resulting from the presence and activity of a microbial, viral, or parasitic agent in humans. "The S1P signaling has already been demonstrated to be affected by various infectious diseases through the alteration of expressions or activities of related enzymes, particularly SPHK1." (PMID 34635791, 2021).
SPHK1 also shares sentences with these, for which no sentence is quoted: COVID-19 (4 papers); hematological malignancies (4); lung adenocarcinoma (4); cardiovascular diseases (3); acute kidney injury (2); adrenocortical carcinoma (2); Allergy (2); bronchopulmonary dysplasia (2); cholangiocarcinoma (2); colorectal tumor (2); fetal macrosomia (2); fibrosis (2); Hodgkins lymphoma (2); metastatic colorectal cancer (2); metastatic melanoma (2); neurological diseases (2); type 1 diabetes (2); -dependent (1); acute erythroleukemia (1); acute lung injury (1); acute respiratory distress syndrome (1); adrenomyeloneuropathy (1); autism (1); autoimmune thyroiditis (1); Autoimmunity (1); benign ovarian tumours (1); biliary tract cancer (1); breast adenocarcinoma (1); breast invasive carcinoma (1); Chronic colitis (1).
A further 60 diseases each share a sentence with SPHK1 in 1 paper.